NRP1 (neuropilin 1)
Diseases named in the same sentence as NRP1 in open-access papers (continued):
Sharing a sentence is not in itself a finding about the gene and the disease.
tumor (continued). "iRGD is recruited to the tumor vessels by interaction with integrins, and after this, it is cleaved by tumor-associated proteases to expose the CendR motif to allow interaction with NRP-1." (PMID 37111665, 2023). "We want to know the associations between the abundance of tumor-infiltrating lymphocytes (TILs) and expressions of NRP1 across human cancers, so an integrated repository portal for TISIDB was applied for the analysis." (PMID 38138098, 2023). "The Sema3A/NRP1 axis contributes to promote angiogenesis, recruitment of tumor-associated macrophages, and tumor-induced immune privilege." (PMID 37788099, 2023). "As well as αvβ3, NRP-1 is often overexpressed in tumors, where it is implicated in multiple processes that promote tumor growth and invasiveness." (PMID 37287910, 2023). "In summary, we established an effective strategy to screen oncolytic viruses from live-attenuated vaccines and confirmed that the tumor tropism of PRV-LAV was associated with the NRP1/EGFR signaling pathway." (PMID 37891570, 2023). "NRP1 expression in tumor-associated MΦs is reduced in hypoxia, and angiogenesis is inhibited through prevention of MΦ migration." (PMID 37847559, 2023). "Association of NRP1 expression levels with tumor stages in human HCC was also evaluated, finding a significant increased expression of NRP1 in advanced HCC stages from UALCAN and GEPIA databases." (PMID 36376373, 2023). "Crosstalk between NRP-1, ITGB3 and FAK was also found earlier in a mouse model, where the suppression of ITGB3 was associated with am NRP-1-dependent change in focal adhesion remodeling in endothelial cells and reduced tumor angiogenesis." (PMID 37175499, 2023). "Type-II IFN can promote tumor response to ICB immunotherapy by inducing the generation of intratumoral neuropilin-1-deficient Tregs." (PMID 35558516, 2022). "In our model, Vesencumab was administered at the time of tumor xenografting until study endpoint to establish the effects of NRP1 inhibition on tumor latency and growth kinetics, as suggested by its association with a mammary stem cell population." (PMID 35078508, 2022). "This supports the interest of NRP1 as a potential therapeutic target to overcome these tumor-associated characteristics." (PMID 35884516, 2022). "Nrp1 expression has been associated with increased tumor angiogenesis through The Cancer Genome Atlas (TCGA) analysis." (PMID 36203599, 2022). "The NRP1 inhibition efficiency associated with RT was evaluated in an orthotopic xenograft model to take into consideration the influence of the tumor microenvironment." (PMID 36457009, 2022). "Upon entry into the hypoxic niche, Nrp1 is downregulated, thereby reducing Sema3A-mediated migratory responses, and trapping the tumor associated macrophages in the hypoxic niche." (PMID 36203599, 2022). "NRP1 overexpression in cancer cells has been associated with tumour aggressiveness, enhanced cell proliferation, and metastasis." (PMID 35955539, 2022). "Tumor angiogenesis is considered an important phenomenon in the progression of tumors and is associated with overexpression of Neuropilin1 (NRP1) receptors." (PMID 35686121, 2022). "Tumor growth was monitored, and it was found that miR-378c-agomir-induced loss of tumor volume and weight was partly rescued by NRP1 or NORAD overexpression." (PMID 35164743, 2022). "Following this regimen, we observed a similarly severe impediment to tumor growth and angiogenesis following the combined loss of endothelial NRP1 and NRP2." (PMID 36970722, 2022). "The group found that hypoxia induced Sema3A-mediated chemoattraction for tumor-associated macrophages through the VEGFR/Nrp1/PlexinA1/PlexinA4 receptor complex." (PMID 36203599, 2022). "Heterogeneity removal led to a significant association of high NRP1 expression with tumor pathogenesis in these cases." (PMID 35884516, 2022).
tumor (continued). "Approximately half (50.40%) of the patients included in this study showed NRP1 overexpression, showing a significant association between NRP1 high levels and both enhanced tumor malignant characteristics and consistent shorter survival." (PMID 35884516, 2022). "Altogether, the differences in plasma, tissue and PBMC profiles suggest that NRP-1 has multiple cell type-specific roles in BC, being a risk factor in plasma and tumor tissue and a protective factor in PBMCs." (PMID 35158858, 2022). "Using DMBA/TPA treatment to induce papillomas, Nrp1 deficient and control mice were compared in their ability to drive tumor initiation and progression." (PMID 36203599, 2022). "In their NRP1-deficient mouse model, they suggest that the loss of NRP1 expression by macrophages and/or microglia is associated with delayed tumor growth." (PMID 34277411, 2021). "Our findings are consistent with previous research showing that Neuropilin-1 is expressed by pulmonary endothelial cells and by tumor-associated vascular endothelial cells (TAVECs)." (PMID 33540664, 2021). "As reported by a previous work that M2 macrophage polarization is associated with the hypoxia TME and thus promotes tumor growth, we further uncover the specific molecules involved in these processes, including NRP1/NRP2 and LAMP1 expressed on TAMs." (PMID 34676217, 2021). "Nrp1 deficiency inhibited TAM recruitment to hypoxic niches that abrogated tumor growth, metastasis, and angiogenesis and activated T-cell response in vitro and in vivo." (PMID 34209679, 2021). "In vitro inhibition of NRP-1 by a photosensitizing peptide resulted in malfunctioning tumor vasculature caused by vasoconstriction, release of tissue factor, and the formation of thrombi." (PMID 33395426, 2021). "IFN-γ produced by Nrp1-deficient (Nrp1-/-) Tregs decreases the stability of surrounding wild-type Tregs and enhances anti-tumor immunity." (PMID 34367136, 2021). "Western blot was further performed to confirm the dysregulation of certain known tumor-associated genes in T24 cells with NRP1 knockdown." (PMID 34249735, 2021). "In the frame of this thinking, low tumor NRP1 expression in mCRC (NO16966 trial) seems to be associated with improved PFS with similar findings for sNRP1 in various studies." (PMID 34298648, 2021). "This study shows that a knockdown of NRP2 has more anti-tumor effects than a knockdown of NRP1, as loss of NRP2 decreases cell proliferation while loss of NRP1 influences cell migration." (PMID 34277411, 2021). "Expression of NRP-1 on these tumor-infiltrating immune cells has been linked to several functions, most of them associated with tumor promotion." (PMID 33266104, 2020). "In the case of tumor-associated macrophages (TAMs), NRP-1, together with PlexinA1/A4, acts as a guide for these cells to migrate to the hypoxic core of the tumor in response to semaphorin 3A (Sema3A), where they exert tumor-promoting functions." (PMID 33266104, 2020). "The presence of trans VEGFR2/NRP1 complexes or perivascular NRP1 expression was associated with a reduced tumor vessel density and size." (PMID 31880322, 2020). "Excessive expression of NRP-1 is associated with progression of disease as well as tumor metastasis." (PMID 33149867, 2020). "NRP1 expression in tumor cells in the discovery cohort showed a decreased risk of cancer‐related death (hazard ratio [HR] = 0.5, 95% confidence interval [CI] = 0.3–0.9, p‐value = 0.03)." (PMID 31880322, 2020). "In the current study, we revealed that NRP1 was highly expressed in GC tumor tissues and was associated with poor prognosis in GC patients." (PMID 32508529, 2020). "Neuropilin-1 can be expressed on tumor cells, tumor-infiltrating myeloid and lymphoid cells and has been linked to a tumor-promoting environment." (PMID 33266104, 2020). "NRP-1 expression in immune cells such as tumor-associated macrophages, T lymphocytes, and dendritic cells is related to tumor growth, migration, and cell‒cell interaction." (PMID 30978940, 2019).
tumor (continued). "Nrp-1 deficiency on murine FoxP3+ CD4+ Treg cells has been reported to delay tumour growth correlated with enhanced activation of tumour-infiltrating CD8+ T cells." (PMID 31350404, 2019). "Neuropilin 1 (NRP1) is extensively expressed in tumor vasculature, where its overexpression has been associated with tumor progression and poor clinical outcome." (PMID 31417646, 2019). "In particular, application of MTP-NRP1 was shown to inhibit NRP1 and associated receptors, thereby blocking downstream signaling and reducing tumor angiogenesis." (PMID 31652529, 2019). "NRP1 is expressed in several human tumors where its high levels are associated with invasive tumor growth and worsened clinical outcome." (PMID 31652529, 2019). "Nrp-1 is also highly expressed on tumour vasculature, functioning as a mediator of tumour initiation and progression, associated with poor clinical outcome." (PMID 31350404, 2019). "The lysosomal degradation of NRP-1 causes decreased tumor angiogenesis and decreased tumor growth in vivo." (PMID 31374919, 2019). "The mechanism of the differential outcome in these two experimental systems is likely associated with the capacity of anti-Nrp-1 to enhance T-cell migration and recruitment within the tumour." (PMID 31350404, 2019). "Hypoxia-regulated neuropilin-1 (Nrp1), a marker of pro-angiogenic macrophages, can regulate the infiltration of TAMs into tumor hypoxic regions, and loss of Nrp1 in macrophages reduced angiogenesis and tumor growth." (PMID 29560266, 2018). "Overexpression of NRP-1 has also been observed in several other cancer types and is associated with tumor progression and poor patient prognosis." (PMID 29728077, 2018). "The neuropilin-1 (NRP-1) receptor has recently been implicated in tumor progression of MB, which seems to play an important role in the phenotype of cancer stem cells." (PMID 29632646, 2018). "PlGF also induces ERK1/2 phosphorylation through NRP1 and causes tumor growth and spread in medulloblastoma." (PMID 29659486, 2018). "Surprisingly, CD8+ T cell-restricted Nrp1-deficient mice showed significantly enhanced protection following B16.F10 tumor challenge, despite unchanged primary tumor growth prior to resection." (PMID 30400822, 2018). "The B16F10 tumor growth in the CD8-restrictive Nrp1-deficient mice (Nrp1L/LE8ICre) was assessed upon initial inoculation, as well as re-challenge after surgical removal of the primary tumors." (PMID 30400822, 2018). "Although the precise mechanism for VEGF binding to NRP-1 in angiogenesis and in endothelial function remains to be unveiled, pre-clinical studies have linked NRP-1 blockade to suppression of tumour growth by blocking angiogenesis." (PMID 29162137, 2017). "We found that NRP1 shRNA expressing KRASmt tumor cells caused increased cell viability by decreasing SMAD2 phosphorylation." (PMID 29018205, 2017). "The role of NRP-1 thus appears to be specific to the compartments it is expressed in; acting as a risk factor in plasma and tumor tissue and as a protective factor in PBMCs." (PMID 28607365, 2017). "For instance, mAb that specifically blocks VEGF165 binding to b1/b2 domain and thereby complex formation between VEGFR2 and NRP1, affected tumor-associated angiogenesis and tumor growth." (PMID 29067024, 2017). "Consistent with the findings in cancer biology research, NRP1 is also tightly linked with tumor progression in clinic." (PMID 27863391, 2016). "As Nrp1-dependent pathways can play a role in the behavior of tumor-associated macrophages in the periphery, we examined the phenotypic state of the GAMs by assessing them for expression of CD86, CD206, and TSPO, which are markers of inflammatory status." (PMID 26755653, 2016). "Our data showed a clear decrease in Nrp-1 obviously in IL10-deficient tumor-bearing mice, and the number of CD4+Foxp3+Nrp-1+ T cells obtained from the spleen was significantly decreased in IL10−/− B16/F10 mice based on flow cytometry analysis." (PMID 27075020, 2016).
tumor (continued). "Surprisingly, abrogation of IL-10 led to the promotion of tumor-associated Nrp-1 expression on CD4+ T cells only after TGF-β Ab treatment." (PMID 27075020, 2016). "A putative mechanistic schematic representation is shown to summarize the effect of endothelial cell loss and gain of NRP-1 on EndMT and tumor fibrosis." (PMID 27542226, 2016). "Increased levels of NRP-1 are correlated to tumor aggressiveness and are associated with poor prognosis." (PMID 27047798, 2016). "LKB1 depletion significantly increased tumor growth in association with elevated NRP-1 expression and angiogenesis." (PMID 26701889, 2016). "In vivo, loss of NRP-1 attenuated tumor perfusion and size, accompanied by reduction in EndMT and fibrosis." (PMID 27542226, 2016). "Neuropilin 1 is expressed by a wide variety of human tumour cell lines and diverse human neoplasms, and is implicated in mediating the effects of VEGF on the proliferation, survival and migration of cancer cells." (PMID 26147006, 2015). "NRP-1 is expressed not only in tumor-associated vessels but also in a variety of cancers suggesting a role in tumor progression." (PMID 26090340, 2015). "Neuropilin 1 was extensively expressed in tumour vasculature, where NRP1 over-expression is associated with tumour progression and poor clinical outcome." (PMID 26147006, 2015). "The results indicate that NRP1 has a key role in tumor progression and that NRP1 expression is associated with lymph node metastasis." (PMID 24999732, 2014). "Spearman correlation analysis further showed that high peritumoral NRP-1 or VEGFR-2 expression was negatively associated with tumor size (NRP-1: r = −0.588, p < 0.001; VEGFR-2: r = −0.455, p < 0.001)." (PMID 25333267, 2014). "NRP-1 shRNA also caused significant inhibition of NRP-1 protein expression in xenograft tumor tissue." (PMID 23251257, 2013). "An elevated NRP-1 protein expression has been associated with a worse prognosis in several tumor entities." (PMID 24086736, 2013). "The depletion of Foxp3+ T cells and disruption of VEGF production on tumor cells mimic the phenotype seen in CD4+ T-cell specific Nrp1-deficient mice." (PMID 24324469, 2013). "NRP-1 is overexpressed in tumors, both in cancer cells and in stromal cells, and is implicated in development and maintenance of the tumor vessels and in tumor growth and progression." (PMID 23986882, 2013). "In tumor settings, there is only scant data describing Nrp-1 expression in association with sub-phenotypes of Treg cells." (PMID 23874336, 2013). "Nrp1 is expressed in numerous cancer types and is usually associated with a bad prognosis due to its role in tumor angiogenesis and migration." (PMID 24386482, 2013). "NRP1 monoclonal antibody has been shown to effectively inhibit tumor vascular remodeling, rendering vessels more susceptible to anti-VEGF therapy." (PMID 20085644, 2010). "Next to reduced Treg cell numbers, the diminished Nrp-1 expression by Treg cells could cause a deficit in the migration of Treg cells to the tumor." (PMID 40977681, 2025). "This indicates that NRP-1 may be associated not only with survival but also with tumor aggressiveness." (PMID 40430075, 2025). "Therefore, in this study, we analyzed the expression patterns of NRP1 and glial markers in MB tissue and evaluated their associations with tumor morphology, molecular subgroup, and clinical behavior." (PMID 40805120, 2025). "Research in our lab indicates that the rapamycin (mTOR) pathway plays a crucial role in VEGF synthesis, and its disruption along the VEGF/NRP1 axis has been linked to the activation of proangiogenic and protumerogenic signaling in both endothelial cells and ccRCC tumor cells." (PMID 40277760, 2025). "Furthermore, molecular studies in mice show that the PIGF/NRP1 pathway promotes angiogenesis and tumor aggressiveness in all subtypes, with NRP1 expression being associated with poor prognosis." (PMID 40805120, 2025).
tumor (continued). "Similarly, miR-124-3p reduces NRP-1 levels in colon cancer cells, and its low level is associated with more aggressive tumor features and poorer clinical prognosis." (PMID 40430075, 2025). "NRP1 has been described lately as a potential target for immune checkpoint inhibition, specifically due to its association with Treg (regulatory T) cells in the tumor microenvironment." (PMID 40649716, 2025). "In this context, NRP1 (neuropilin-1) is associated with EMT in multiple tumor types." (PMID 38920653, 2024). "NRP-1 has been detected on tissue-resident macrophages as well as on tumor-associated macrophages (TAMs), where it plays a critical role in their migration to the tumor hypoxic niche in response to SEMA3A." (PMID 39857591, 2024). "Elevated NRP1 levels in serum may reflect its increased expression in tumor tissue and serve as a useful diagnostic marker for detecting cancer and monitoring its progression." (PMID 39334861, 2024). "However, NRP1 overexpression in tumor cells is associated not only with angiogenesis but also with PCa cells developing resistance to androgen-targeted therapy and progression to metastatic castration-resistant prostate cancer (mCRPC)." (PMID 37371647, 2023). "Additionally, we interestingly reveal significant associations between NRP1 expressions and the tumor–immune response in immune lymphocytes, chemokines, receptors, immunostimulators, immune inhibitors, and MHC molecules in almost all pan cancers." (PMID 38138098, 2023). "GBM biopsies have revealed that the increased expression of NRP-1 is associated with malignancy, whereas reducing its expression suppresses migration, proliferation, and survival in vitro and stem cell viability and tumor growth in vivo." (PMID 36986856, 2023). "Patients with high expression of NRP1 had poor survival and the results of gene set enrichment analysis also showed that the high-risk group was highly correlated with tumor metastasis, which is consistent with other reports that NRP1 is involved in regulating the metastasis of various tumors." (PMID 37702613, 2023). "NRP-1 overexpression may also increase tumor growth and is often associated with poor prognosis, especially in tumors of epithelial origin." (PMID 35056995, 2022). "In contrast to Nrp1, tumor-associated Tregs were universally Helios+." (PMID 35523809, 2022). "NRP1 mutation analysis across different tumor types was carried out in TIMER2.0." (PMID 36338984, 2022). "Investigating the spatial positioning of the tumor associated macrophages with knock-out and WT macrophages, the group reported that Sema3A drives tumor associated macrophage trafficking into areas of hypoxia in a Nrp1-dependent manner." (PMID 36203599, 2022). "Neuropilin-1 receptor (NRP1) has been implicated in the tumor progression of MB." (PMID 36457009, 2022). "Consequently, mice with Nrp1-deficient Tregs display enhanced anti-tumor immunity and tumor clearance, prolonged survival and increased responsiveness to anti-PD-1 therapy without autoimmune abnormalities." (PMID 34394124, 2021). "Although the epithelial mesenchymal transition after radiation in H1299 needs to be further investigated, there is also a possibility of the association of up-regulation of NRP-1 in IR cells with the enhancement of the tumor migration and invasion caused by the radiation-derived EMT." (PMID 34698100, 2021). "In glioma, Nrp1 is expressed by tumour-associated microglia and affects tumour progression." (PMID 33741250, 2021). "Herein, high-expressed NRP1 was detected in a variety of BC cell lines by qRT-PCR and human BC tissues by IHC, whose overexpression has been reported to be associated with tumor progression and poor prognosis in patients with BC; however, the underlying molecular mechanisms remain poorly understood." (PMID 34249735, 2021). "Whether FUBP1 is associated with NRP1 expression in tumor-infiltrated lymphocytes remains more discussion." (PMID 33987449, 2021).